CTNNA3 (catenin alpha 3)
Description:
May be involved in formation of stretch-resistant cell-cell adhesion complexes.
Synonyms: VR22; MGC26194; ARVD13
Tractability: No criterion of Open Targets' tractability assessment is met for any kind of drug.
Gene: Protein-coding gene on chromosome 10 (65,912,457 to 67,763,637, reverse strand). Ensembl gene ENSG00000183230.
Subcellular location: Cytoplasm, cytoskeleton; Cell junction, desmosome
Gene Ontology:
Molecular function: beta-catenin binding; protein binding; actin filament binding; cadherin binding
Biological process: bundle of His cell-Purkinje myocyte adhesion involved in cell communication; cell-cell adhesion; regulation of heart rate by cardiac conduction; regulation of ventricular cardiac muscle cell action potential; cell migration; cell adhesion
Cellular component: fascia adherens; adherens junction; cytoskeleton; desmosome; lamellipodium
Genetic constraint (gnomAD): Loss-of-function variants: 55 observed, 78.65 expected, observed/expected ratio (o/e) 0.7, 90% interval 0.56 to 0.88. The upper end of that interval is the gene's LOEUF score, 0.88, which puts it in group 3 of 6, group 1 being the genes least tolerant of losing a copy. Missense variants: 1,043 observed, 1,001.3 expected, observed/expected ratio (o/e) 1.04, 90% interval 0.99 to 1.1. Synonymous variants: 386 observed, 349.91 expected, observed/expected ratio (o/e) 1.1, 90% interval 1.01 to 1.2.
Gene-disease validity (ClinGen):
ClinGen rates the evidence that CTNNA3 causes each of these diseases.
arrhythmogenic right ventricular cardiomyopathy (autosomal dominant): Limited.
congenital heart disease (inheritance undetermined): Disputed. A heart disease that is present at birth.
Homologues: Orthologues: chimpanzee CTNNA3 (99% identical), macaque CTNNA3 (99% identical), dog CTNNA3 (96% identical), pig CTNNA3 (95% identical), guinea pig CTNNA3 (95% identical), rabbit CTNNA3 (95% identical), mouse Ctnna3 (94% identical), rat Ctnna3 (92% identical), Drosophila melanogaster alpha-Cat (51% identical), Caenorhabditis elegans hmp-1 (37% identical). Paralogues in human: CTNNA2 (61% identical), CTNNA1 (60% identical), VCL (21% identical), CTNNAL1 (17% identical).
Diseases named in the same sentence as CTNNA3 in open-access papers:
CTNNA3 is named in the same sentence as 95 diseases in open-access papers, as found by Europe PMC text mining. Sharing a sentence is not in itself a finding about the gene and the disease. The quoted sentences say what the papers report.
autism (9 papers, 2010 to 2023). Persistent deficits in social interaction and communication and interaction as well as a markedly restricted repertoire of activity and interest as well as repetitive patterns of behavior. "However, numerous genetic association studies have linked CTNNA3 to a wide spectrum of diseases, ranging from asthma and food allergy to autism, multiple sclerosis, diabetes and Alzheimer's." (PMID 36420826, 2022). "Moreover, a similar sequence of events to this was observed with respect to the convergent transcription of the overlapping LRRTM3 and CTNNA3 genes associated with autism." (PMID 34440463, 2021). "Two genome-wide association studies implicated common variants in CTNNA3 in autism susceptibility." (PMID 25050139, 2014). "Many of these CNVs encompass genes included in the best‐known lists of candidate genes for autism, including CTNNA3 (OMIM #607667), MACROD2 (OMIM #611567), IMMP2L (OMIM #605977), PARK2 (OMIM #600116), LZTS2 (OMIM #610454), and LRP1 (OMIM #107770)." (PMID 37186221, 2023). "Recent genetic association studies have linked the cadherin-based adherens junction protein alpha-T-catenin (αT-cat, CTNNA3) with the development of autism." (PMID 27330745, 2016). "In a recent genome-wide scan performed by the AGP in the largest family-based sample of ASD reported to date, we have identified a compound heterozygous deletion encompassing the CTNNA3 gene in a male proband with autism." (PMID 25050139, 2014). "Given the discovery of a compound heterozygous deletion of exon 11 in CTNNA3 in a male proband with autism, we examined the frequency of CTNNA3 exonic deletions in autism and control populations." (PMID 25050139, 2014). "In the second stage of the Autism Genome Project (AGP) genome-wide study, amounting to approximately 1,600 ASD families, we detected one rare compound heterozygous deletion involving the CTNNA3 gene, encoding αT-catenin, in a proband with autism." (PMID 25050139, 2014). "We compared the frequency of CTNNA3 exonic deletions in 2,147 ASD cases from the Autism Genome Project (AGP) study versus the frequency in 6,639 controls." (PMID 25050139, 2014). "Some of the genes, such as NCAN and EPHA7, have similar functionality as NRXN1 in mediating neuronal cell interactions, while some other genes, such as PCDH19, CNTN3, CTNNA3, LMX1B, are known autism candidate genes." (PMID 23536886, 2013). "Moreover, in a recent analysis of exon-disrupting CNVs affecting known autism candidate genes, CTNNA3 was found borderline enriched in the autism cohort as opposed to controls (22 out of 2,588 autism cases versus 12 out of 2,670 controls, P = 0.050)." (PMID 25050139, 2014).
schizophrenia (8 papers, 2014 to 2022). A major psychotic disorder characterized by abnormalities in the perception or expression of reality. "CTNNA3 gene has roles implicated in the formation of stretch-resistant cell-cell adhesion complexes and is reported for causing mental ailments such as schizophrenia, besides the gene is reported to be expressed in the cerebellum." (PMID 32680568, 2020). "The CTNNA3 (catenin alpha-3) gene was associated with the risk of schizophrenia and intracellular signaling through beta-catenin translocation and AKT/PKB pathways have implicated in antidepressant-induced hippocampal cell proliferation." (PMID 27091189, 2016). "Among the 29,000 SNPs, the rs7902091 in the CTNNA3 gene was found to significantly interact with maternal cytomegalovirus infection in causing schizophrenia after correcting for the number of tests performed." (PMID 24860514, 2014). "The first systematic search for gene–environment interactions has found that a polymorphism in CTNNA3 may sensitize the developing brain to the pathogenic effect of cytomegalovirus in utero, leading to schizophrenia in adulthood." (PMID 24860514, 2014).
Alzheimer disease (7 papers, 2010 to 2023). A progressive, neurodegenerative disease characterized by loss of function and death of nerve cells in several areas of the brain leading to loss of cognitive function such as memory and language. "For example, the most top selected SNPs in HGM-FS method in multiclass classifications come from gene “CTNNA3,” which is a protein-coding gene and is associated to late-onset Alzheimer's disease." (PMID 25368574, 2014). "Another disease-associated gene is CTNNA3, which has been shown to be associated with other psychiatric disorders, such as general cognitive ability, and Alzheimer’s disease." (PMID 23382809, 2013). "LRRTM3 is a nested gene within α-T catenin (CTNNA3) and resides at the linkage peak for late-onset Alzheimer’s disease (LOAD) risk and plasma amyloid β (Aβ) levels." (PMID 23750206, 2013). "CTNNA3 is a cell adhesion gene that has been associated with Alzheimer's disease." (PMID 20546594, 2010).
arrhythmogenic right ventricular cardiomyopathy (7 papers, 2015 to 2025). "Mutations in CTNNA3 have been identified in families with arrhythmogenic right ventricular dysplasia, autism spectrum disorder, and several carcinomas." (PMID 31170158, 2019). "CTNNA3 gene mutation could cause arrhythmogenic right ventricular dysplasia, compound heterozygous deletion was related to ASD." (PMID 28472932, 2017). "According to the test results, cousins (IV:1 and IV:2) have the same variants in ABCG8 (intronic), CTNNA3, and RASA1 genes, involved in the pathogenesis of arrhythmogenic right ventricular cardiomyopathy (CTNNA3) and RASA1 (capillary malformations, Park Weber syndrome)." (PMID 33829027, 2021). "The CTNNA3 gene is a new candidate gene for arrhythmogenic right ventricular cardiomyopathy (ARVC)." (PMID 33829027, 2021). "The enrichment analysis for cardiac dysfunction in patients with myocardial injury with Impala has shown that catenin alpha 3 is related to arrhythmogenic right ventricular cardiomyopathy (p-value = 0.01 with non-significant q-value)." (PMID 34640372, 2021).
asthma (7 papers, 2011 to 2022). "With regards to CTNNA3 linkages to steroid-resistant asthma, our team previously validated this association showing that Ctnna3KO mice display reduced airway hyperreactivity in response to methacholine challenge." (PMID 36420826, 2022). "A number of genome-wide association studies have linked CTNNA3 to chemical-induced occupational asthma, steroid refractory asthma and asthmatic exacerbations." (PMID 36420826, 2022). "Soon afterward, another group investigated the association of CTNNA3 with asthma and confirmed that CTNNA3 is expressed in the lung and their knock-out mouse model was hyperresponsive to methacholine." (PMID 36276967, 2022). "In children, polymorphisms in CTNNA3 correlated with asthma response to therapy, in particular ICS treatment, rather than to asthma genetic susceptibility." (PMID 33925009, 2021). "recently a GWAS identified CTNNA3 as a susceptibility gene for airway hyperresponsiveness in toluene diisocyanate induced asthma, and mutations in CTTNA3 have been implicated in NSCL cancer." (PMID 24023788, 2013). "Our group previously validated αT-cat's linkage to steroid-resistant asthma using the house-dust mite model, where Ctnna3 knock-out mice showed greatly attenuated airway hyperreactivity." (PMID 36420826, 2022). "For example, genome-wide association studies have identified cardiac-related genes, including CTNNA3 (encoding α-T-catenin) and TTN (encoding titin), as a factor for the pathogenesis or exacerbation of asthma." (PMID 34867960, 2021). "Indeed, our team validated αT-cat's linkage to asthma using the house-dust mite model, where Ctnna3 knock-out mice showed greatly attenuated airway hyperreactivity." (PMID 36420826, 2022).
dilated cardiomyopathy (6 papers, 2014 to 2025). Cardiomyopathy which is characterized by dilation and contractile dysfunction of the left and right ventricles. "Deletion of cardiac cytosolic protein CTNNA3 in the mouse has been associated with dilated cardiomyopathy and actomyosin dysregulation in the heart." (PMID 33262348, 2020). "Patient SS1, presenting with a dilated cardiomyopathy (DCM) with conduction defects (OMIM#115200) harbored a 3.74 kb deletion that resulted in the heterozygous loss of the alpha-T-catenin gene (CTNNA3)." (PMID 26214305, 2015). "CTNNA3 has been considered as a candidate for the form of dilated cardiomyopathy linked to 10q21q23 (CMD1C; 601493) because of its high expression in the heart." (PMID 24297458, 2014). "The Ctnna3-null mice are viable and fertile and show no obvious macroscopic phenotypic abnormality; however, they exhibit early-onset progressive dilated cardiomyopathy, gap junction remodelling and increased risk of cardiac arrhythmia." (PMID 25050139, 2014). "For example, mutations in JUP, DSP, PKP2, DSG2, DSC2, CTNNA3, CDH2, or PLN (all of them more abundant in LV) predominantly lead to arrhythmogenic right ventricular cardiomyopathy, and mutations in MYH7, HSPB7, NEXN and MYPN (also all more abundant in LV) lead to dilated cardiomyopathy." (PMID 32291283, 2020).
breast carcinoma (5 papers, 2010 to 2023). "This identified thirty-one unique genes, of which five have previously been associated with breast cancer (LGR6, NR3C2, LOC105377563, CTNNA3, PRIM1)." (PMID 37345113, 2023). "Theα-catenin coding genes, CTNNA1, CTNNA2 and CTNNA3, participate carcinogenesis of multiple cancers, such as laryngeal carcinomas, oropharyngeal squamous cell carcinomas and breast cancer." (PMID 26882563, 2016). "Our results have shown the expressional association and clinical relevance of six genes (CDH2, FN1, CITED2, CTNNB1, and CTNNA3) together with GRHL2 for breast cancer metastases." (PMID 23441166, 2013). "Two of these genes, CTNNA3 and PRIM1, have been previously associated with breast cancer." (PMID 37345113, 2023). "Among the altered genes, ARHGAP26 and MLLT1 have been associated with leukemia-specific translocations, DDHD2, FGFR1 and PTPN1 have tumor-promoting potential in breast cancer, and CTNNA3 may promote tumor formation in urothelial cancer." (PMID 20428235, 2010). "Training on public gene expression profiles of 995 breast cancer patients, this method prioritized one gene-set pair (GRHL2, CDH2, FN1, CITED2, MKI67 versus CTNNB1 and CTNNA3) from all 2717 possible gene-set pairs (GSPs)." (PMID 23441166, 2013). "Importantly, few of these proteins, namely, ATP1B2, CTNNA3 and MYLK were reported to be downregulated biomarkers in glioma, hepatocellular and breast carcinoma, respectively." (PMID 34728699, 2021).
cardiomyopathy (3 papers, 2015 to 2021). A disease of the heart muscle or myocardium proper. "CTNNA3 (Catenin α 3) encodes a protein within the vinculin family of cell-cell adhesion proteins, and has been linked with certain types of cardiomyopathy." (PMID 34208743, 2021). "Several reports link variants in the CTNNA3 gene with another form of cardiomyopathy, specifically, arrhythmogenic right ventricular dysplasia (ARVC; OMIM#107970)." (PMID 26214305, 2015).
hepatocellular carcinoma (3 papers, 2016 to 2021). A malignant tumor that arises from hepatocytes. "miR-425 was up-regulated in hepatocellular carcinomas cells, and forced expression of miR-425 promoted proliferation and migration by inhibiting CTNNA3 hepatocellular carcinomas cell." (PMID 34124998, 2021). "Moreover, miR-425 can inhibit hepatocellular carcinomas by targeting the cell–cell adhesion gene of CTNNA3." (PMID 31708963, 2019).
laryngeal carcinoma (3 papers, 2016 to 2021). Carcinoma that arises from the laryngeal epithelium. "CTNNA3 is a tumor suppressor and frequently mutates in laryngeal carcinomas and low-expressed in urothelial carcinoma of the bladder." (PMID 26882563, 2016). "CTNNA2 and CTNNA3 are also frequently mutated tumor suppressor genes in laryngeal cancer." (PMID 34163353, 2021). "CTNNA2 is a tumor suppressor gene frequently mutated in laryngeal cancer, and CTNNA2 and CTNNA3 mutations increase the migration and invasion capabilities of head and neck squamous cell carcinoma cells." (PMID 34163353, 2021).
Brugada syndrome (2 papers, 2021 to 2022). A genetically heterogeneous condition characterized by complete or incomplete right bundle branch block accompanied by ST elevation in leads V1-V3. "Indeed, even CTNNA3's linkages to heart disease merit revisiting, where recent linkages to atrial fibrillation/Brugada Syndrome may be due to a peripheral nerve rather than a cardiomyocyte junction defect." (PMID 36420826, 2022).
colorectal cancer (2 papers, 2014 to 2018). A primary or metastatic malignant neoplasm that affects the colon or rectum. "On the other hand, a previous GEWIS reported that interactions of rs12870649 at 13q14.1 (CTNNA3) and rs9409565 at 9q22.32 (HIATL1) with alcohol consumption were associated with colorectal cancer risk." (PMID 29464080, 2018).
head and neck squamous cell carcinoma (2 papers, 2018 to 2021). A squamous cell carcinoma that arises from any of the following anatomic sites: lip and oral cavity, nasal cavity, paranasal sinuses, pharynx, larynx, and salivary glands. "CTNNA2 and CTNNA3 encode for cell-cell adhesions, and are thought to be tumor suppressors which are frequently mutated and implicated in head and neck squamous cell carcinoma." (PMID 30557297, 2018).
leukaemia (2 papers, 2010 to 2017). "The CTNNA3 gene has been shown to be linked to the Shwachman-Diamond syndrome which is characterized by a high risk of leukaemia." (PMID 28303531, 2017). "Information, which has been found in the course of literature research, coincides to some extent with information about CTNNA3 and GABRE gene involvement in branches of diseases associated with leukaemia." (PMID 28303531, 2017).
meningioma (2 papers, 2020 to 2024). A generally slow growing tumor attached to the dura mater. "In two cases, the identification of entity-specific fusions suggested a re-classification of a meningioma CNS-WHO grade 2 to intracranial mesenchymal tumor (ATF1::ESWR1 fusion) and glioblastoma to a polymorphous low-grade neuroepithelial tumor of the young (PLNTY, FGFR2::CTNNA3 fusion)." (PMID 39143272, 2024).
metabolic syndrome (2 papers, 2021 to 2023). A cluster of metabolic risk factors for CARDIOVASCULAR DISEASES and TYPE 2 DIABETES MELLITUS. "In a recent genome-wide association study on Metabolic Syndrome of African Lineage (MetS), single nucleotide polymorphism (SNPs) of CTNNA3 were reported can be new genetic signals of metabolic syndrome risk." (PMID 34717601, 2021). "Additionally, prior African ancestry GWAS found CTNNA3 to be associated with metabolic syndrome." (PMID 37345113, 2023).
myositis (2 papers, 2019 to 2022). "Explaining biological insight for ADE-associated noncoding variants remains challenging, and the specific pathways leading to the association between CTNNA3 and the occurrence of myositis need further functional investigation." (PMID 30420678, 2019). "The discovery of a new relationship between CTNNA3 and myositis among individuals treated with oxicams warrants further studies of its mechanistic pathways." (PMID 30420678, 2019). "This population-based study of >2200 individuals identified a novel intronic variant of the Catenin alpha 3 (CTNNA3) gene associated with myositis and myopathies in individuals taking nonsteroidal anti-inflammatory oxicams." (PMID 35693792, 2022). "Specifically, we found that CTNNA3 was associated with myositis and myopathies among individuals taking nonsteroidal anti-inflammatory oxicams and replicated this finding in an extended cohort of 706 individuals." (PMID 30420678, 2019).
Age-related cataract (1 paper, 2021). A type of cataract (opacification of the lens) that forms during the course of aging. "Some of these genes associated with age-related cataracts include FRMD4B, NAALADL2, LOC105377670, LINC00968, LOC101929415, CTNNA3, LOC107984170, PRCP, and ZNF423, whereas others with a reduced risk include CFAP74, ACSL1, LOC101927668, LOC105369844." (PMID 34299682, 2021).
Anxiety (1 paper, 2021). Intense feelings of nervousness, tension, or panic often arise in response to interpersonal stresses. "Other genes previously linked to mood, anxiety, or trauma-related disorders included protein zeta-1 (FEZ1), ADCYAP1, BRSK2, catenin alpha 3 (CTNNA3), and par-3 family cell polarity regulator (PARD3)." (PMID 34799556, 2021).
Bradycardia (1 paper, 2021). A slower than normal heart rate (in adults, slower than 60 beats per minute). "Results from gene prioritization analysis highlight two genesRYR3 and CTNNA3 that may play a role in sinus bradycardia induced by SGAs." (PMID 33914752, 2021).
bronchitis (1 paper, 2019). An acute or chronic inflammatory process affecting the bronchi. "Given the broad range of phenotypes ascribed to CTNNA3, it is important to note that obligate carrier II-7 developed bronchitis, cancer and osteoporosis, whereas III-10 and III-11 developed cancer and rheumatic fever, respectively, in addition to MS." (PMID 31170158, 2019).
ciliopathy (1 paper, 2022). A genetic disorder of the cellular cilia or the cilia anchoring structures, the basal bodies, or of ciliary function. "Eight direct known interactions were found between HLHS candidates and ciliopathy-associated genes (HLHS candidates are shown in bold): TSC22D1-UNC119, RPTOR-CILK1, MFSD6-TMEM237, EP300-CRX, CTNNA3-CRX, CTNNA3-FAM161A, NIF3L1-NME7 and TSC1-GLIS2, and one direct novel interaction, RPTOR-CCDC40." (PMID 35456433, 2022).